EIF4A3 (eukaryotic translation initiation factor 4A3)
Diseases named in the same sentence as EIF4A3 in open-access papers (continued):
Sharing a sentence is not in itself a finding about the gene and the disease.
glioblastoma (24 papers, 2018 to 2025). The most malignant astrocytic tumor (WHO grade IV). "High EIF4A3 expression was associated with poor outcomes of anti-PD-1 treatment in melanoma and glioblastoma, but showed positive outcomes of adoptive T cell therapy and anti-PD-1 treatment in melanoma." (PMID 37777564, 2023). "Studies have reported that EIF4A3 is elevated in many tumors, such as glioblastoma, hepatocellular carcinoma, pancreatic cancer and ovarian cancer." (PMID 38459513, 2024). "In Glioblastoma, EIF4A3 can enhance the stability of LINC00680 and TTNAS1, facilitate the cyclization of circMMP9, and upregulate its expression, thereby promoting tumor proliferation, migration, and invasion." (PMID 37777564, 2023). "Wang et.al firstly confirmed that EIF4A3 involved in circMMP9 cyclization by uniting with its matrix metalloproteinase-9 (MMP-9) mRNA transcript in glioblastoma multiforme." (PMID 37626035, 2023). "Another study in glioblastoma showed that EIF4A3 can regulate the expression of hsa_circ_0001162 (circMMP9) by binding to an upstream mRNA region." (PMID 34458150, 2021). "Several recent studies have shown that EIF4A3 promotes tumor growth in multiple human cancers such as glioblastoma, hepatocellular carcinoma, pancreatic cancer, and ovarian cancer." (PMID 34458150, 2021). "EIF4A3 is overexpressed in glioblastoma and is related to two lncRNAs, LINC00680 and TTNAS1, that promote the malignant behavior of glioblastoma cells." (PMID 34458150, 2021). "Recent studies have shown that EIF4A3 is overexpressed in various tumors, such as glioblastoma, HCC, PAAD, and ovarian cancer, where the interaction between lncRNAs and EIF4A3 plays an important oncogenic role." (PMID 34458150, 2021). "EIF4A3-induced circMMP9 is a circular RNA involved in glioblastoma cell proliferation, invasion, and metastasis." (PMID 34458150, 2021). "EIF4A3 is also highly expressed in many tumors, such as glioblastoma, hepatocellular carcinoma (HCC), pancreatic cancer, and ovarian cancer, and it can be recruited by long non-coding RNAs (lncRNAs) to stabilize proteins and promote tumorigenesis." (PMID 34458150, 2021). "Notably, eIF4A3 was previously reported to induce the expression of circASAP1 and circMMP9 in glioblastoma." (PMID 35135542, 2022). "Moreover, several researches have revealed that EIF4A3 executes carcinogenic properties in glioblastoma and ovarian cancer." (PMID 31541081, 2019). "Thus, EIF4A3 may induce the formation of circMMP9 by binding to circMMP9 mRNA, increasing the expression of circMMP5 in glioblastoma and promoting tumor progression." (PMID 34458150, 2021). "In addition, these findings suggest that the tumor-promoting role of EIF4A3 in glioblastoma may be related to the upregulation of ceRNAs." (PMID 34458150, 2021). "For instance, exosomal circ-AHCY recruited EIF4A3 to stabilize TCF4 mRNA and facilitated glioblastoma cell growth via the Wnt signaling pathway." (PMID 39858034, 2025). "Eukaryotic translation initiation factor 4A3 (EIF4A3) belongs to the RNA-binding protein family, and has been reported to be related to the tumorigenesis of glioblastoma." (PMID 38771413, 2024). "Recent studies have illustrated that EIF4A3 is upregulated in different cancers, including hepatocellular carcinoma (HCC), glioblastoma, pancreatic cancer and CRC." (PMID 37940881, 2023). "A recent study confirmed that EIF4A3 played a role in the EIF4A3/CASC2/RORA loop and ultimately facilitated the aggressive phenotype of glioblastoma." (PMID 35936722, 2022). "For example, it was found that EIF4A3 directly combines with the MMP9 mRNA transcript, accelerates circMMP9 cyclization, and increases circMMP9 levels in glioblastoma multiforme." (PMID 36138395, 2022). "circASAP1 expression stimulated by EIF4A3 elevates glioblastoma development via the ERK pathway, and E2F1- and EIF4A3-induced circSEPT9 expression accelerates triple-negative breast cancer progression." (PMID 36138395, 2022).
glioblastoma (continued). "EIF4A3 bound to the MMP9 mRNA transcript, inducing circMMP9 cyclization and increasing circMMP9 expression in glioblastoma multiforme." (PMID 34930906, 2021). "Eukaryotic initiation factor 4A3 (eIF4A3) induces circMMP9 expression by binding to MMP9 pre‐mRNA and also promotes glioblastoma multiform proliferation and metastasis." (PMID 33687144, 2021). "Wang et.al reported that EIF4A3 could bind to the MMP9 mRNA transcript, facilitate circMMP9 cyclization and enhance circMMP9 expression in glioblastoma multiforme." (PMID 32264877, 2020). "That study showed that when the expression of EIF4A3, LINC00680, and TTNAS1 was downregulated in PANC-1 and SW1990 cells, their proliferation, migration, and invasion was impaired, while tumor growth was inhibited in vivo and glioblastoma cell apoptosis was promoted." (PMID 34458150, 2021).
hepatocellular carcinoma (22 papers, 2021 to 2025). A malignant tumor that arises from hepatocytes. "In hepatocellular carcinoma, loss-of-function assays have shown that the silencing of eIF4A3 inhibits cell proliferation, migration, and EMT." (PMID 34869305, 2021). "The YTHDF1/EIF3C axis is involved in the invasion process in ovarian cancer; EIF3H participates in the invasion of hepatocellular carcinoma and the EIF4A3/FLOT1 pathway promotes invasion and tumor proliferation in lung adenocarcinoma." (PMID 40705973, 2025). "The EIF4A3/circFADS1/GSK3β/β‐catenin axis is discovered to hold promise as a novel therapeutic target for hepatocellular carcinoma, while circFADS1 is also a significant factor in lenvatinib resistance." (PMID 39965082, 2025). "Though a clear mechanism remains elusive, EIF4A3-induced circRHBDD1 is also upregulated in hepatocellular carcinoma patients and predicts poor response to anti-PD-1 treatment." (PMID 39550559, 2024). "Recent studies have shown that eIF4A3 is significantly upregulated in several malignant tumors, such as hepatocellular carcinoma, pancreatic cancer, and ovarian cancer." (PMID 35677890, 2022). "Hsa_circ_0005397 promotes progression of hepatocellular carcinoma through EIF4A3." (PMID 38383334, 2024). "For example, it promotes atg4b-mediated autophagy and attenuates sorafenib sensitivity in hepatocellular carcinoma cells; it regulates eIF4A3/MUC1/EGFR signalling and modulates the response of EGFR-mutant lung cancer to EGFR tyrosine kinase inhibitor resistance." (PMID 35359593, 2022). "eIF4A is the most abundant subunit of eIF4F with RNA-dependent ATPase and RNA helicase activity, playing an important role in the initiation of protein synthesis Studies have demonstrated that eIF4A3 is overexpressed in a variety of tumors, including melanoma, hepatocellular carcinoma, and lymphoma." (PMID 35546509, 2022). "EIF4A3 and E1A binding protein p300 (EP300) synergistically promote the biogenesis of circCCAR1 in hepatocellular carcinoma." (PMID 39550559, 2024).
gastric cancer (18 papers, 2011 to 2025). A primary or metastatic malignant neoplasm involving the stomach. "In addition to its indirect association with gastric cancer, EIF4A3 appears to act as a regulatory factor of other key genes related to cancer progression." (PMID 34458150, 2021). "It was also verified that circ_0008126 inhibited gastric cancer proliferation and metastasis in a miR-502-5p and EIF4A3-dependent manner by attenuating the APC/β-catenin pathway, which extends our understanding of the dual regulatory pathway of circRNA." (PMID 39858034, 2025). "The mechanism by which circGLIS3 is regulated by EIF4A3 provides a comprehensive understanding of the pathogenesis of gastric cancer." (PMID 38459513, 2024). "EIF4A3 is significantly upregulated in gastric cancer and has been reported to play a tumor-promoting role in a variety of tumors." (PMID 38459513, 2024). "In gastric cancer, EIF4A3 binds to circRNA_0074027, promoting the proliferation and migratory capacity of tumor cells." (PMID 37576389, 2023). "We also noticed that the growth rate of gastric cancer cells was continuously promoted by the presence of EIF4A3." (PMID 38093288, 2023). "Some studies have confirmed that EIF4A3 can enhance the proliferation and metastasis of gastric cancer." (PMID 37322413, 2023). "The cyclization of hsa_circ_001988 stimulated by EIF4A3 decreases gastric cancer development by sponging miR-197-3p." (PMID 36138395, 2022). "Based on cDNA microarrays differential expression of eIF4A3 in gastric cancer tissues has been reported." (PMID 21347291, 2011). "LINC01016 could affects downstream protein expression by binding to EIF4A3 and promotes the progression of gastric cancer." (PMID 39881131, 2025). "In conclusion, we identified circGLIS3, which could be regulated by EIF4A3, to be upregulated in gastric cancer tissues and to correlate positively with gastric cancer progression." (PMID 38459513, 2024). "When we overexpressed EIF4A3 in gastric cancer cells, the expression of circGLIS3 increased, which proved that EIF4A3 could indeed promote the generation of circGLIS3." (PMID 38459513, 2024). "QRT-PCR experiments showed that overexpression of EIF4A3 could promote hsa_circ_0136666 expression, while knockdown of EIF4A3 could suppress the expression of hsa_circ_0136666 in gastric cancer cells." (PMID 38093288, 2023). "For example, the RBP EIF4A3 inhibits the formation of circRNA_100290 by binding to it, and in gastric cancer, dysregulation of this regulatory mechanism would lead to the increased level of this circRNA, which triggers downstream activities such as tumor cell proliferation." (PMID 36072601, 2022). "On the contrary, a recent study found that EIF4A3 could inhibit the expression of circ_100290 in gastric cancer." (PMID 34696782, 2021). "Therefore, EIF4A3 plays an important role in the process of circGLIS3 splicing, and revealing the generation mechanism of circGLIS3 will help us better understand the deep mechanism of abnormal circRNA expression in gastric cancer." (PMID 38459513, 2024). "Before investigating the relationship between EIF4A3 and LINC01016 in the progression of gastric cancer, we first evaluated the role of EIF4A3 in this carcinogenic context." (PMID 39881131, 2025). "Additionally, multiple studies have demonstrated the overexpression of eIF4A3 in various malignancies, including HCC, gastric cancer, epithelial ovarian cancer, and ovarian cancer." (PMID 38238581, 2024). "In summary, EIF4A3-mediated circ_0008126 inhibited gastric cancer proliferation and metastasis in a miR-502-5p- and EIF4A3-dependent manner by attenuating the APC/β-catenin pathway, providing a potential target for the pathogenesis of GC and anti-cancer therapy." (PMID 39858034, 2025).
triple-negative breast carcinoma (16 papers, 2020 to 2026). An invasive breast carcinoma which is negative for expression of estrogen receptor (ER), progesterone receptor (PR), and human epidermal growth factor receptor 2 (HER2). "The circRNA circSEPT9 mediated by E2F1 and EIF4A3 facilitates the carcinogenesis and development of triple-negative breast cancer." (PMID 37410095, 2023). "The RT-qPCR assay showed that overexpression of EIF4A3 facilitated the expression of circSEPT9, while EIF4A3 knockdown inhibited circSEPT9 expression in triple-negative breast cancer cells." (PMID 34930906, 2021). "EIF4A3 has also been reported to promote the formation of circSEPT9 and promote the development of triple-negative breast cancer." (PMID 33262952, 2020). "Our data reveal that the circSEPT9 mediated by E2F1 and EIF4A3 facilitates the carcinogenesis and development of triple-negative breast cancer through circSEPT9/miR-637/LIF axis." (PMID 32264877, 2020). "Additionally, circSEPT9 mediated by E2F1 and EIF4A3 propels the carcinogenesis and progression of triple-negative breast cancer via the circSEPT9/miR-637/LIF axis." (PMID 38956466, 2024). "For example, circSEPT9 regulated by E2F transcription factor 1 (E2F1) and eukaryotic translation initiation factor 4A3 (EIF4A3) pushes the cancerous derivation of triple-negative breast cancer through the circSEPT9/miR-637/Leukemia Inhibitory Factor (LIF) axis." (PMID 34540684, 2021). "For instance, it was recently found that E2F1 and EIF4A3 might promote the biogenesis of circSEPT9 and the occurrence and development of triple-negative breast cancer by acting on the miR-637/LIF axis." (PMID 33323543, 2020). "In triple-negative breast cancer, E2F1 and EIF4A3 promoted high expression of circRNA circSEPT9, which in turn promoted cell proliferation, invasion, tumorigenesis, and metastasis in vivo." (PMID 37322413, 2023). "The expression of circRNAs can be regulated by transcription factors; for example, circSEPT9 expression in triple-negative breast cancer cells is mediated by E2F1 and EIF4A3." (PMID 36072902, 2022). "From all the RBPs investigated, seven were differentially expressed and upregulated (AGO2, EIF4A3, ELAVL1, IGF2BP2/3, LIN28B, and U2AF2), showing that these genes have an important role in triple-negative breast cancer development." (PMID 35805051, 2022).
lung cancer (11 papers, 2021 to 2026). A malignant neoplasm involving the lung. "Overexpression of EIF4A3 mRNA is linked to poor prognosis in breast and lung cancer, and EIF4A3‐selective inhibitors have been studied as potential cancer therapy with promising results in xenograft mice." (PMID 37591798, 2023). "CRNDE and DGCR5 (DiGeorge Syndrome Critical Region Gene 5) lncRNAs, highly expressed in EGFR‐TKI‐resistant lung cancer cells, bind eukaryotic translation initiation factor 4A3 (EIF4A3) in an overlapping manner." (PMID 37042179, 2023). "CRNDE contributes to the resistance to EGFR tyrosine kinase inhibitor in EGFR-mutant lung cancer through eIF4A3/MUC1/EGFR signaling." (PMID 37194105, 2023). "Although miR-214-3p’s exact role in LUAD is not fully understood, CircTADA2A can trap miR-214-3p and eukaryotic translation initiation factor 4A3 (EIF4A3) to boost mitogen-activated protein kinase 8 (MAPK8) levels, promoting invasion and migration in lung cancer cells." (PMID 40191724, 2025). "Furthermore, siRNAs-mediated knockdown of EIF4a3 significantly decreased circRABL2B expression and increased MUC5AC level in lung cancer cells." (PMID 37324942, 2023). "Consistently, TCGA data demonstrated a negative correlation between expressions of EIF4a3 and MUC5AC in lung cancer." (PMID 37324942, 2023).
ovarian carcinoma (11 papers, 2019 to 2025). A malignant neoplasm originating from the surface ovarian epithelium. "Quantitative proteomics analysis showed that ivermectin can suppress EIF4A3 and 116 EIF4A3-associated proteins in ovarian cancer." (PMID 34458150, 2021). "In epithelial ovarian cancer cells, eIF4A3 binds CASC2 and enhances cell viability, apoptosis, migration, and invasion." (PMID 34869305, 2021). "In epithelial ovarian cancer, eIF4A3 is highly expressed in cancer tissues compared to adjacent normal tissues." (PMID 34869305, 2021). "In summary, the binding of EIF4A3 to lncRNAs inhibits the ability of EIF4A3 to target mRNAs, thus favoring ovarian cancer progression." (PMID 34458150, 2021). "Studies of EIF4A3-related ovarian cancer have focused on the molecular mechanisms of antitumor drugs." (PMID 34458150, 2021). "For instance, SNHG3 is related to energy metabolism by regulating eukaryotic translation initiation factor 4A3 (EIF4A3) mRNA in ovarian cancer (OC)." (PMID 33292213, 2020). "Overexpression of CASC2 inhibited epithelial ovarian cancer development by inhibiting EIF4A3 expression and suppressing the PI3K/AKT/mammalian target of rapamycin (mTOR) pathway." (PMID 31134151, 2019). "That work has shown that sanguinarine and ivermectin can regulate the lncRNA-EIF4A3-mRNA axis, suggesting that they might have anti-ovarian cancer activity and that EIF4A3 may participate in the progression of ovarian cancer." (PMID 34458150, 2021). "B. Inhibition of Translation: In ovarian cancer (OC), SNHG3 regulates eukaryotic translation initiation factor 4A3 (EIF4A3) mRNA, implicating its role in energy metabolism and tumor progression." (PMID 39349640, 2024). "In ovarian cancer, there is upregulation of EIF4A3, whereas suppression of PPP2R2C leads to ovarian cancer cell proliferation." (PMID 35628146, 2022). "Notably, eIF4A3 has been identified as a binding protein of lncRNA CASC2, thereby affecting epithelial ovarian cancer development." (PMID 34869305, 2021).
cervical cancer (10 papers, 2009 to 2025). A primary or metastatic malignant neoplasm involving the cervix. "Given the good prognosis linked to high levels of eIF4A3 in cervical cancers, it would be interesting in the near future to quantify E6 and E7 expression levels in patients and determine whether we can find a correlation with the levels of expression of eIF4A3." (PMID 33760064, 2021). "In cervical cancer, the expression of circ-0087429, which is induced by eIF4A3, reverses the EMT process and inhibits the malignant progression of the disease." (PMID 39085875, 2024). "In our study, we found that EIF4A3 regulated the expression of TCAM1P, which means high expression of TCAM1P in cervical cancer is regulated by EIF4A3." (PMID 35016697, 2022). "It just so happens that our previous data does show that EIF4A3 is involved in the occurrence of cervical cancer." (PMID 35016697, 2022). "First, we evaluated the prognostic value of eIF4A3 expression in cervical cancers using TCGA database." (PMID 33760064, 2021). "Of the 26 upregulated proteins, 3 were upregulated in vaginal carcinoma only, compared with normal vaginal tissue and cervical cancer (DEAD box protein (DDX48 or EIF4A3), erbB3-binding protein (Ebp1) and biliverdin reductase)." (PMID 19367286, 2009). "If this correlation can be detected, we could then hypothesize that a loss of eIF4A3 function, along the evolution of HPV-induced carcinogenesis, could favor an overexpression of these oncoproteins and cervical cancer development." (PMID 33760064, 2021). "According to the TCGA database, we showed that the levels of the EJC factor eIF4A3 could be considered as an indicator of good prognosis in cervical cancers." (PMID 33760064, 2021). "To determine whether eIF4A3 could regulate HPV16 gene expression, we performed siRNA-mediated depletion of eIF4A3 in the HPV16-positive cervical carcinoma SiHa cell line." (PMID 33760064, 2021). "Furthermore, EIF4A3 has been shown to inhibit circ_0087429 expression by binding to its flanking regions, leading to enhanced proliferation, migration, invasion, and angiogenesis in cervical cancer." (PMID 38771413, 2024). "EIF4A3-regulated circ_0087429 can reverse EMT and inhibit cervical cancer progression via miR-5003-3p-dependent up-regulation of OGN expression." (PMID 38814453, 2024). "In summary, EIF4A3-downregulated circ_0087429 is a tumour suppressor gene that can promote the expression of OGN and inhibit the EMT of cervical cancer cells by competitively binding miR-5003-3p." (PMID 35513835, 2022). "As a tumour suppressor, circ_0087429 regulated by EIF4A3 can reverse EMT and inhibit the progression of cervical cancer through the miR-5003-3p/OGN axis." (PMID 35513835, 2022). "Moreover, we verified the relationship between TCAM1P and HPV and confirmed that HPV E6/E7 and EIF4A3 can regulate the expression of TCAM1P, which promoted the proliferation of cervical cancer cells." (PMID 35016697, 2022).